PPARG (peroxisome proliferator activated receptor gamma)
Diseases named in the same sentence as PPARG in open-access papers (continued):
Sharing a sentence is not in itself a finding about the gene and the disease.
cyst (9 papers, 2010 to 2022). A sac-like closed membranous structure that may be empty or contain fluid or amorphous material. "In kidney samples of mice, rats and humans, and in 3D cyst cultures, mRNA expression of these pioglitazone targets appeared to be substantially higher than observed for PPARγ." (PMID 32015419, 2020). "In the inflammatory animal model and cyst formation cell model, studies reported the activating effect of PPARγ by curcumin is attributed to its ability to reduce the intracellular protein p-ERK." (PMID 23544048, 2013). "We then introduced a PPARγ siRNA into ADPKD cyst-lining epithelial cells by transfection." (PMID 22174924, 2011). "Moreover, PPARγ agonists appear to be effective not only in the kidney but in other tissues where cyst formation and growth are dependent on CFTR-driven ion and fluid secretion." (PMID 21052534, 2010). "Based on the previous finding that PPARγ agonists inhibit CFTR expression, the current studies were designed to test the efficacy of a PPARγ agonist, pioglitazone, in inhibiting cyst growth." (PMID 21052534, 2010). "This indicates that PPARγ is not required for pioglitazone to reduce cyst swelling in 3D cysts." (PMID 32015419, 2020). "Although these findings may at least explain some of the PPARγ-independent cyst-reducing effects of pioglitazone in our 3D cyst assay and in PCK rats, it does not provide an explanation for the lack of efficacy in our PKD mouse model." (PMID 32015419, 2020). "In the present study, we show that the expression of the most obvious pioglitazone target PPARγ across different models and species is not consistent with whether or not pioglitazone exerts cyst inhibiting effects." (PMID 32015419, 2020). "In addition, pioglitazone, a peroxisome proliferator-activated receptor γ (PPARγ) agonist inhibited vasopressin-induced chloride secretion through reducing CFTR mRNA levels in MDCK-C7 cell line and suppressed cyst progression by decreasing apical CFTR expression in PCK rodent model of PKD." (PMID 23536832, 2013). "To determine whether or not the action of rosiglitazone on human ADPKD cyst-lining epithelial cells was mediated by PPARγ, we used both pharmacological and genetic approaches." (PMID 22174924, 2011). "But whether PPARγ agonists can block TGF-β1 pathway in ADPKD cyst-lining epithelia have not been studied until now." (PMID 22174924, 2011).
dyslipidaemia (9 papers, 2007 to 2022). "The role of PPARγ in the treatment of dyslipidaemia has been shown in clinical trials." (PMID 34887761, 2021).
endotoxemia (9 papers, 2007 to 2023). "15d-PGJ2-induced PPARγ activation also exacerbates pulmonary edema and tissue injury associated with LPS-induced endotoxemia by locally elevating chemokine and IL-1β expression and increasing the number of mucin-producing cells." (PMID 27774097, 2016). "BBR also inhibited inducible cyclooxygenase-2 (COX-2) overexpression in rat small intestinal mucosa via activation of the peroxisome proliferator-activated receptor-gamma (PPARγ) pathway and inhibited the effects of LPS in a rat model of endotoxemia." (PMID 36741234, 2023). "Therefore, in this experiment we explored whether baicalin would regulate iNOS and NO expression in small intestinal mucosa via modulation of p38 and/or PPARγ pathways in a rat model of acute endotoxemia." (PMID 24312512, 2013). "Therefore, upregulation of PPARγ might be a feedback mechanism of self-protection during acute endotoxemia." (PMID 24312512, 2013). "Furthermore, PPARγ-mediated upregulation of SIRT1 expression participates in the inhibitory action of PPARγ through deacetylation-mediated interaction of SIRT1 and HMGB1, leading to improvement of the survival of endotoxemia model mice." (PMID 28403838, 2017).
familial partial lipodystrophy type 3 (9 papers, 2017 to 2025). "Type 3 Familial Partial Lipodystrophy (FPLD3) is a rare metabolic disease related to pathogenic PPARG gene variants." (PMID 38951919, 2024). "The loss-of-function mutations in human PPARG results in the development of familial partial lipodystrophy type 3 (FPLD3) and other serious metabolic anomalies." (PMID 33511131, 2020). "Selected sequence variants in the PNR LBD associated with human retinopathies, or a mutation in the dimerization region of PPARγ LBD associated with familial partial lipodystrophy type 3, were found to disrupt PNR/PPARγ complex formation." (PMID 28300834, 2017). "Interestingly, subjects with familial partial lipodystrophy type 3, a disease linked to pathogenic variants in PPARG, have striking clinical similarity to our proband with IMPA." (PMID 33210059, 2020). "Rare sequence variants in the PPARγ LBD, such as V318M, F388L, R425C and P495L, are associated with familial partial lipodystrophy type 3." (PMID 28300834, 2017).
lipoma (9 papers, 2014 to 2024). A benign, usually painless, well-circumscribed lipomatous tumor composed of adipose tissue. "PPARγ and C/EBPα were positive in all tumors of each LS type, but the cells expressing these proteins were somewhat more common in undifferentiated myxoid areas than in lipoma-like components." (PMID 25650275, 2015). "PPARγ was found to be over-expressed in DDLPS by immunostaining too and PPARδ was also found highly expressed in LPS compared to lipoma." (PMID 36557266, 2022). "Although there are no studies on gene expression in isolated cells some research groups investigated the differences in expression of ADIPOQ, LEP and PPARG, RUNX2 and BGLAP in lipoma tissue and compared it with normal adipose tissue." (PMID 30544806, 2018). "The quantification of the bound ORO staining unequivocally revealed that lipoma-derived ASCs have a significantly weaker capacity to differentiate into the adipogenic direction as confirmed by downregulated FABP4, PPARγ, and LEP expression compared to ASCs of RP and SC fat." (PMID 31640774, 2019). "In our study, both PPARγ and C/EBPα were found in each type of LSs with or without mature lipoma-like components." (PMID 25650275, 2015).
neuropathy (9 papers, 2014 to 2025). A disorder affecting the nervous system that manifests with pain, tingling, numbness, and/or muscle weakness. "One of the exciting and valuable publications is a review in which the authors present the issues related to chemotherapy-induced neuropathy and the effects of PPARγ activation in treating chemotherapy-induced neuropathic pain." (PMID 39062500, 2024). "This review focuses largely on the mechanisms involved in chemotherapy-induced neuropathy and the effects of the activation of PPARγ to treat CINP." (PMID 31555078, 2019). "The optimal profile shown by the lower dosage suggests the mild stimulation of PPARγ as possible approach to the oxaliplatin neuropathy." (PMID 25036594, 2014). "Peroxisome stimulation by the PPARγ agonist rosiglitazone was analyzed to individuate new possible pharmacological approaches to control oxaliplatin-induced neuropathy." (PMID 25036594, 2014). "Recent works have focused on the role of lipid metabolism in the development of neuropathy and the use of pharmacological agents that target lipid metabolism, such as pioglitazone, a peroxisome proliferator-activated receptor gamma (PPARG) agonist with well-described antidiabetic effects." (PMID 30616626, 2019).
thyroid tumor (9 papers, 2004 to 2025). A benign or malignant neoplasm affecting the thyroid gland. "We further showed that both flank and orthotopic thyroid tumors derived from PPARγ-depleted cells grew more slowly than PPARγ-expressing cells." (PMID 22194735, 2011). "Our results demonstrated that PPARγ is underexpressed in translocation-negative thyroid tumours of follicular origin and that a further reduction of PPARγ expression is associated with dedifferentiation at later stages of tumour development and progression." (PMID 15238980, 2004). "We have expanded our previous study and analysed the expression of PPARγ in a series of thyroid tumours and correspondent normal tissue by reverse transcription–polymerase chain reaction (RT–PCR), interphase fluorescent in situ hybridisation (FISH), real-time RT–PCR and immunohistochemistry." (PMID 15238980, 2004). "In summary, we have demonstrated underexpression of PPARγ in PAX8/PPARγ-negative thyroid tumours of follicular origin, and that a further reduction of PPARγ expression is associated with dedifferentiation at later stages of tumour development." (PMID 15238980, 2004). "We observed that PPARγ expression is usually underexpressed in multiple types of thyroid tumours, and that this may be an important event in the development of thyroid neoplasias." (PMID 15238980, 2004). "Therefore, it is expected that the expression pattern of PAX8/PPARγ fusion protein is associated with the differentiation behaviour of thyroid tumours, where absent or low level is expected in poorly differentiated tumours and high level in well-differentiated tumours." (PMID 39558949, 2024). "Notably, PPARγ fusions, primarily PAX8::PPARγ, are observed in 25–45% of follicular-patterned thyroid neoplasms, whereas CREB3L2::PPARγ is exceedingly rare and present in less than 3% of such tumors." (PMID 40839045, 2025). "We and others have detected cases of thyroid tumours, such as FTC, FTA or PTC, that exhibit mild or moderate diffuse PPARγ nuclear staining, even though they are RT–PCR negative for the PAX8-PPARγ fusion gene." (PMID 15238980, 2004).
urothelial carcinoma (9 papers, 2013 to 2025). A malignant neoplasm derived from the transitional epithelium of the urinary tract (urinary bladder, ureter, urethra, or renal pelvis). "Counterintuitively, few studies have investigated GATA3 as a regulator of PPARγ expression in the context of urothelial carcinoma." (PMID 37250326, 2023). "This study is to investigate the role of peroxisome proliferator-activated receptor γ (PPARγ) in the progression of urothelial carcinoma (UC) after renal transplants (RT)." (PMID 33289586, 2020). "The exact contribution of PPARG to the etiology of the basal subtype of urothelial carcinoma is less clear." (PMID 31597917, 2019). "Some studies have suggested that PPARG-dependent transcriptional regulation may be involved in the etiology of urothelial carcinoma, and decreasing PPARG activity via drug inhibition or gene ablation inhibits the proliferation of BC cells." (PMID 36131343, 2022). "These analyses reveal alterations in PPARG expression and signaling, suggesting that PPARG-dependent transcriptional regulation may be important in the etiology of urothelial carcinoma." (PMID 31597917, 2019). "Support for such a role for SHH signaling comes from studies in urothelial carcinoma cells, in which SHH overexpression after PPARG inhibition resulted in a partial rescue of cell proliferation and migration/invasion." (PMID 40167323, 2025). "Among a consecutive series of pT2 urothelial carcinoma patients, our system identified four molecular subtypes using CD44, CK5/6, CK20, and pPARγ." (PMID 35805028, 2022). "Basal urothelial carcinoma shows a positive stain for CD44 and CK5/6, and a negative stain for CK20 and pPARγ, whereas luminal urothelial carcinoma shows an opposite pattern." (PMID 35805028, 2022). "We have also determined the dose response of among the urothelial carcinoma cell lines (UM-UC1, UM-UC3, UM-UC5, UM-UC6, UM-UC13, RT4, 253JP, 253J-BV, KU7) to different concentrations of EGFR inhibitor (gefitinib) and PPARγ agonist (DIM-C) after 72 hs of treatment." (PMID 23409107, 2013). "However, the effect of PPARγ on calpain-2, MMP2 and MMP9 in urothelial carcinoma is unknown and remains to be elucidated." (PMID 33289586, 2020).
acute lung injury (8 papers, 2015 to 2025). A condition of lung damage that is characterized by bilateral pulmonary infiltrates (pulmonary edema) rich in neutrophils, and in the absence of clinical heart failure. "Here, we investigated the role of the PPARγ agonist in the lung to find out whether it can regulate AFC during acute lung injury (ALI)." (PMID 31160894, 2019).
acute respiratory distress syndrome (8 papers, 2010 to 2025). Progressive and life-threatening pulmonary distress in the absence of an underlying pulmonary condition, usually following major trauma or surgery. "The upregulation of HO-1 induced by PPARγ mediated the inflammatory response in acute lung injury/acute respiratory distress syndrome." (PMID 39856769, 2025). "Another study revealed that electroacupuncture pretreatment at Hegu (LI4) could alleviate LPS-induced acute respiratory distress syndrome via regulating the PPARγ/NF-kB signaling pathway." (PMID 38104066, 2023). "In LPS-induced acute lung injury/acute respiratory distress syndrome (ALI/ARDS), α-ketoglutarate could inhibit M1 polarization by suppressing the mTORC1/p70S6K pathway and promote the M2 phenotype by enhancing PPARγ nuclear translocation, which is conducive to preventing inflammatory diseases." (PMID 33859536, 2021).
airway hyperresponsiveness (8 papers, 2005 to 2025). "In summary, to our knowledge, this is the first study demonstrating that MAG‐DPA interacts with TNF‐α/NFκB and PPARγ signaling pathways to mediate resolving properties in human and rodent models of airway hyperresponsiveness." (PMID 28097001, 2016). "Administration of peroxisome proliferator-activated receptor gamma (PPARgamma) agonists or AdPPARgamma reduced bronchial inflammation and airway hyperresponsiveness by up-regulating PTEN expression in allergen-induced asthmatic lungs." (PMID 21489309, 2011). "In addition, a variety of in vitro experiments have demonstrated that PPARG can regulate mucinous proteins and inflammatory cytokines in lung tissue, thereby exaggerating the expression of airway hyperresponsiveness, inflammation, and cytokines." (PMID 34211564, 2021).
bipolar depression (8 papers, 2016 to 2026). "Similar benefits were also obtained with rosiglitazone as an adjunct therapy in bipolar depression, suggesting that PPARγ could potentially modulate mood and emotion." (PMID 31614690, 2019).
colon adenocarcinoma (8 papers, 2006 to 2025). "Tumor-associated stroma cells are known to differ from their normal counterparts in the expression of various biologically molecules such as PPARγ, which was found to be upregulated in stromal myofibroblasts of colon adenocarcinomas." (PMID 23049949, 2012). "Previous studies have shown ANGPTL4, through its regulation by short chain fatty acid and peroxisome proliferator-activated receptor γ (PPARγ), may play a role in the progression of colon adenocarcinoma." (PMID 39811640, 2025). "HT-29 cells are colon adenocarcinoma cells that robustly express PPARγ proteins." (PMID 37047133, 2023). "Moreover, in the human colon adenocarcinoma cell line, it has been shown that mutated K-ras suppressed SSAT via a transcriptional mechanism that involves PPARγ signalling pathway." (PMID 16854216, 2006). "Previously, the comparison of PPARγ expression levels in 11 human colon adenocarcinomas revealed no change in comparison to normal mucosa." (PMID 16854216, 2006).
cystic fibrosis (8 papers, 2011 to 2025). Autosomal recessive disorder caused by pathogenic variants in the CFTR gene (cystic fibrosis transmembrane conductance regulator), which encodes a chloride and bicarbonate channel expressed in epithelial cells, and follow the diagnosis criteria. "We hypothesized that inhibition by 3OC12HSL of the function of an already low level of PPARγ expressed in CF could further exacerbate hyperinflammation in cystic fibrosis." (PMID 22860094, 2012). "In CFPAC-1 cells, derived from a pancreatic ductal adenocarcinoma liver metastasis of a patient with cystic fibrosis, a borderline significant rhythmicity with a 24 h period was found for the PPARG, DNMT1, and DNMT3B expression patterns, and the time-qualified profiles showed different shapes." (PMID 22966223, 2012). "As we add more targets and anti-targets, the number of candidates decreases: we found, among our ∼2.1 million screened molecules, only 374 candidates for combined (simultaneous) CB2R and PPARγ agonism, which may be tested for SSc, dermatomyositis, cystic fibrosis, and IBD." (PMID 35295337, 2022). "In cystic fibrosis, the expression of anti-inflammatory nuclear transcription regulator peroxisome proliferator-activated receptor gamma (PPARγ is low compared to healthy controls, and appears to be reduced further in the presence of P. aeruginosa." (PMID 30114278, 2018). "Because 3OC12HSL is detected in lungs of cystic fibrosis patients infected with P. aeruginosa, we investigated the relationship between P. aeruginosa infection and gene expression of PPARγ and PON2 in bronchoalveolar lavage fluid (BALF) of children with CF." (PMID 22860094, 2012). "The expression and function of PPARγ have been reported to be low in human CF respiratory epithelial cell lines and in cystic fibrosis transmembrane conductance regulator (cftr) knockout mice." (PMID 22860094, 2012).
follicular adenomas (8 papers, 2004 to 2024). "PAX8/PPARγ rearrangements were detected in about 2%–10% of follicular adenomas, as in the fvPTC." (PMID 35197932, 2022). "Chromosomal rearrangement resulting in a fusion gene, PAX8/PPARγ, may be involved in follicular adenoma (FA) to FTC progression." (PMID 27158284, 2015). "The PAX8/PPARγ rearrangement, producing the PAX8–PPARγ fusion protein (PPFP), is rare in follicular adenomas." (PMID 38791384, 2024). "This appears also to be case for PAX8/PPARγ rearrangements, that were originally discovered in FTC and, later on, in follicular adenomas and follicular variant of PTC; PAX8/PPARγ rearrangements are absent from all PDTC and UTC so far analysed." (PMID 22654560, 2011).
gastric ulcer (8 papers, 2010 to 2025). An ulcerated lesion in the mucosal surface of the stomach. "Regarding to gastric disease, this PPARγ polymorphism is associated with not only gastric ulcer but also gastric adenocarcinoma." (PMID 20885923, 2010).